SOX15 (SRY-box transcription factor 15)
Description:
Transcription factor that binds to DNA at the 5'-AACAATG-3' consensus sequence (By similarity). Acts as a transcriptional activator and repressor (By similarity). Binds synergistically with POU5F1 (OCT3/4) to gene promoters (By similarity). Binds to the FOXK1 promoter and recruits FHL3, resulting in transcriptional activation of FOXK1 which leads to myoblast proliferation (By similarity). Acts as an inhibitor of myoblast differentiation via transcriptional repression which leads to down-regulation of the muscle-specific genes MYOD and MYOG (By similarity). Involved in trophoblast giant cell differentiation via enhancement of HAND1 transcriptional activity (By similarity). Regulates transcription of HRC via binding to it proximal enhancer region (By similarity). Involved in skeletal muscle regeneration (By similarity). Also plays a role in the development of myogenic precursor cells (By similarity).
Synonyms: SOX20; SOX26; SOX27
Tractability: No criterion of Open Targets' tractability assessment is met for any kind of drug.
Gene: Protein-coding gene on chromosome 17 (7,588,178 to 7,590,094, reverse strand). Ensembl gene ENSG00000129194.
Subcellular location: Nucleus
Subcellular location (Human Protein Atlas): Nucleoplasm; Nucleoli; Vesicles
Gene Ontology:
Molecular function: protein binding; DNA binding; DNA-binding transcription activator activity, RNA polymerase II-specific; DNA-binding transcription factor activity; DNA-binding transcription factor activity, RNA polymerase II-specific; RNA polymerase II cis-regulatory region sequence-specific DNA binding; chromatin binding
Biological process: brain development; cell differentiation; chromatin organization; male gonad development; myoblast development; negative regulation of striated muscle tissue development; negative regulation of transcription by RNA polymerase II; neuron differentiation; positive regulation of G0 to G1 transition; positive regulation of myoblast proliferation; positive regulation of satellite cell activation involved in skeletal muscle regeneration; positive regulation of transcription by RNA polymerase II; regulation of DNA-templated transcription; regulation of transcription by RNA polymerase II; trophoblast giant cell differentiation
Cellular component: chromatin; nucleus; cytoplasm; transcription regulator complex
Genetic constraint (gnomAD): Loss-of-function variants: 14 observed, 15.14 expected, observed/expected ratio (o/e) 0.92, 90% interval 0.61 to 1.44. The upper end of that interval is the gene's LOEUF score, 1.44, which puts it in group 5 of 6, group 1 being the genes least tolerant of losing a copy. Missense variants: 309 observed, 293.41 expected, observed/expected ratio (o/e) 1.05, 90% interval 0.96 to 1.16. Synonymous variants: 149 observed, 139.08 expected, observed/expected ratio (o/e) 1.07, 90% interval 0.94 to 1.23.
Homologues: Orthologues: chimpanzee SOX15 (99% identical), macaque SOX15 (95% identical), dog SOX15 (85% identical), rabbit SOX15 (77% identical), mouse Sox15 (75% identical), guinea pig SOX15 (73% identical), rat Sox15 (70% identical), zebrafish sox19a (42% identical), zebrafish sox19b (42% identical), Drosophila melanogaster Sox21a (39% identical), tropical clawed frog sox15 (37% identical), Drosophila melanogaster Sox100B (30% identical), and 6 more. Paralogues in human: SOX1 (47% identical), SOX3 (45% identical), SOX2 (44% identical), SOX21 (36% identical), SOX14 (36% identical), SOX9 (34% identical), SOX10 (31% identical), SOX17 (31% identical), SOX18 (30% identical), SOX8 (30% identical), SOX7 (30% identical), SOX11 (30% identical), and 8 more.